YWHAZP3 (tyrosine 3-monooxygenase/tryptophan 5-monooxygenase activation protein zeta pseudogene 3)
Gene: Processed pseudogene on chromosome 10 (23,136,924 to 23,137,661, forward strand). Ensembl gene ENSG00000229932.
Diseases named in the same sentence as YWHAZP3 in open-access papers:
YWHAZP3 is named in the same sentence as 4 diseases in open-access papers, as found by Europe PMC text mining. Sharing a sentence is not in itself a finding about the gene and the disease. The quoted sentences say what the papers report.
juvenile idiopathic arthritis (1 paper, 2024). Juvenile idiopathic arthritis (JIA) is the term used to describe a group of inflammatory articular disorders of unknown cause that begin before the age of 16 and last over 6 weeks. "Additionally, YWHAZP2, YWHAZP3, and YWHAZP10 expression is elevated in a study of LPS-treated PBMC of juvenile idiopathic arthritis patients." (PMID 38674334, 2024).
psoriatic arthritis (1 paper, 2024). Joint inflammation associated with psoriasis. "A study of T cells from the blood and synovial fluid of psoriatic arthritis patients revealed the expression of YWHAZP3 and YWHAZP10 in both leukocytes and T cells; the expression of YWHAZP1, YWHAZP5, and YWHAZP6 in leukocytes only; the expression of YWHAZP2 in T Cells only." (PMID 38674334, 2024).
rheumatoid arthritis (1 paper, 2024). A chronic, systemic autoimmune disorder characterized by inflammation in the synovial membranes and articular surfaces. "Similarly, synovial tissue macrophages from patients in remission from rheumatoid arthritis showed the expression of YWHAZP3, YWHAZP4, and YWHAZP10." (PMID 38674334, 2024).
YWHAZP3 also shares sentences with these, for which no sentence is quoted: autoimmune thrombocytopenia (1 paper).